CRY2 (cryptochrome circadian regulator 2)
Diseases named in the same sentence as CRY2 in open-access papers (continued):
Sharing a sentence is not in itself a finding about the gene and the disease.
glioma (16 papers, 2017 to 2025). A benign or malignant brain and spinal cord tumor that arises from glial cells (astrocytes, oligodendrocytes, ependymal cells). "A reduced level of Cry2 expression was observed in gliomas than the healthy tissues and linked with an increased mortality rate." (PMID 40495887, 2025). "Higher Cry2 expression in glioma tissues was in association with increased cell proliferation and irradiation resistance." (PMID 36066207, 2022). "Where, clock regulatory protein cryptochrome-2 (CRY2) was found to be associated with hampered radiosensitivity of C6 glioma cells." (PMID 32195174, 2020). "Nonetheless, in a rat model, results obtained from irradiated gliomas indicated a link between elevated Cry2 expression and elevated cell proliferation as well as reduced apoptosis." (PMID 40495887, 2025). "Cry2 mRNA and protein levels exhibit 8 h periodicity in glioma tissue compared to 24 h in normal brain tissue." (PMID 36066207, 2022). "In glioma tissues, expression of Cry2 was attenuated compared to healthy samples and correlated with higher mortality." (PMID 34361055, 2021). "Compared with normal brain tissue, CRY2 mRNA and protein levels illustrated aberrant rhythmic periodicity of 8 h in glioma tissues." (PMID 32195174, 2020). "Immunohistochemistry experiments showed that high CRY2 expression in glioma tissues was correlated with increased cell proliferation and decreased apoptosis." (PMID 32195174, 2020). "Similar to PER genes, lower expression of CRY1 and/or CRY2 was observed in gliomas compared with their matched healthy tissues." (PMID 32195174, 2020). "Particularly, the intensity of immunostaining for CRY2 between high-grade gliomas and low-grade gliomas was significantly lower." (PMID 32195174, 2020). "Downregulation of the circadian genes encoding CRY2, PER1, PER2, PER3, CLOCK, REV-ERBβ, ROR-α and ROR-β was associated with significantly higher mortality rates in the glioma cohort, hinting at possible tumor suppressor roles." (PMID 32631383, 2020). "Immunohistochemical staining of Cry2 protein in the glioma and normal brain tissues showed similar pattern as cry2 mRNA." (PMID 29100427, 2017). "The aberrant periodic oscillation in cry2 expression in glioma tissues indicates altered circadian rhythm, which is regulated by SCN." (PMID 29100427, 2017). "In conclusion, our study demonstrates that Cry2 plays a significant role in cell cycle, apoptosis and proliferation of glioma cells." (PMID 29100427, 2017). "To determine the relevance of these changes in cry2 expression on glioma, we measured proliferation and apoptosis of glioma cells when rats were irradiated when Cry2 mRNA and protein levels were high and low." (PMID 29100427, 2017). "The levels of cry 2 mRNA were higher in the irradiated glioma group than in the control glioma group at ZT8 (t = –5.135, p< 0.001) and ZT4(t = –4.464, p < 0.001), which represent high and low cry2 expression time points for glioma brain tissues, respectively." (PMID 29100427, 2017). "In this study, we investigated if Cry2 regulated glioma proliferation and apoptosis treatmented by irradiation." (PMID 29100427, 2017). "Cry2 mRNA and protein levels did not respond to irradiation in normal tissues, but both were increased at the ZT4 (low Cry2) and ZT8 (high Cry2) time points in gliomas." (PMID 29100427, 2017). "In this study, we investigated the role of the clock regulatory protein cryptochrome 2 (Cry2) in determining the radiosensitivity of C6 glioma cells in a rat model." (PMID 29100427, 2017). "In glioma tissues, irrradiation induced high cry2 mRNA expression and disappearance of rhythmicity (F=0.34, P>0.5)." (PMID 29100427, 2017). "We observed that Cry2 mRNA and protein levels showed aberrant rhythmic periodicity of 8 h in glioma tissues, compared to 24 h in normal brain tissue." (PMID 29100427, 2017). "In this study, we demonstrate aberrant expression and circadian rhythm of the clock gene cry2 in the gliomas compared to normal brain tissue." (PMID 29100427, 2017).
glioma (continued). "Next, we measured the effects of irradiation (15Gy) on cell proliferation in glioma and normal brain tissues when CRY2 levels were either high or low by PCNA immunohistochemical analysis." (PMID 29100427, 2017). "Upon irradiation, CRY2 protein expression increased in glioma tissues at ZT4 (t = –5.276, p < 0.001) and ZT8 (t = –6.599, p < 0.001), with loss of rhythmicity (F=0.57, p >0.5)." (PMID 29100427, 2017). "The cry2 expression shows a periodicity of 8h in glioma tissues compared to 24h in normal brain tissues." (PMID 29100427, 2017). "However, findings of irradiated glioma cells in a rat model showed a correlation between the increased expression of Cry2 and increased cell proliferation and decreased apoptosis." (PMID 34361055, 2021). "For Per1 expression, disturbances on rhythmic expression of Cry2 were observed in glioma tissues with a period of 8 h compared to 24-h periodicity displayed by normal brain samples suggesting that an altered rhythmic expression of Cry2 influences sensitivity to irradiation on gliomas cells." (PMID 34361055, 2021). "Expression of CRY1 and CRY2 is lower in HGGs compared to surrounding non-glioma cells." (PMID 32631383, 2020). "Similarly, lower Per2 levels were observed in glioma tissues at ZT4 compared to ZT24 in normal brain tissues when cry2 expression was lowest in both (t=-2.508, p<0.01)." (PMID 29100427, 2017). "However, in the glioma tissues, cry2 mRNA expression was aberrant with two 2 peaks at ZT8 and ZT16 and low at ZT4, ZT12 and ZT20." (PMID 29100427, 2017). "Therefore, aberrantly increased proliferation in glioma tissues correlated with Cry2 mRNA and protein levels." (PMID 29100427, 2017). "Apoptosis in glioma tissue correlated with the level of cry2 expression." (PMID 29100427, 2017). "This is compatible with a hypothesis that CRY2 controls Egr1 gene expression and maybe key to glioma growth and development." (PMID 29100427, 2017). "Similarly, MDM2 levels were higher at ZT4 in glioma tissues compared to ZT24 in normal brain tissues when cry2 expression was lowest (t=-4.361, p<0.001)." (PMID 29100427, 2017). "We observed upregulation of p73 in glioma tissues with the low cry2 expression." (PMID 29100427, 2017). "However, MDM2 levels in glioma tissues at ZT8 were higher than at ZT12 in normal brain tissues when cry2 expression was highest (t=-5.047, p<0.001)." (PMID 29100427, 2017). "For example, the CRY2, ALDH5A1, and ATP6V1G2 tumor suppressor genes are involved in osteosarcoma, ovarian cancer, and glioma, respectively." (PMID 38552216, 2024). "Key CCGs, including ARNTL, NPAS2, CRY2, and DBP, acted as potent diagnosis and prognosis biomarkers of glioma patients and rhythmically regulated cancer-related signaling pathways and coexpressed genes to affect drug sensitivity and possible clinic outcomes." (PMID 35832846, 2022). "The differential expression of CCGs in glioma grading confirmed that cluster I genes (ARNRL, NPAS2, and TIMELESS) and CRY1, with cluster II genes (CRY2, DBP, NR1D1, NR1D2, PER2, PER3, and RORA) showed significantly opposite expression trends in brain tissues." (PMID 35832846, 2022). "WGCNA was performed to identify the genes that were coexpressed with the four key CCGs (ARNTL, NPAS2, CRY2, and DBP) in glioma." (PMID 35832846, 2022). "In summary, we provided a CCGs-based accurate prediction model and showed that ARNTL, NPAS2, CRY2, and DBP had great effects on diagnosis and prognosis of glioma." (PMID 35832846, 2022). "In glioma tissues, the proportion of apoptotic cells was lower (20.1%) at ZT8 when cry2 expression was high compared to 52.6% at ZT4 when cry2 expression was lower (p<0.001)." (PMID 29100427, 2017). "In glioma brain tissues, the proportion of proliferating cells (PCNA+ve) were 69.4% at ZT8 when cry2 expression was maximal compared to 34.7% at ZT4 when cry2 expression was lowest (p<0.01)." (PMID 29100427, 2017).
glioma (continued). "In our study, we irradiated normal tissues at ZT12 and ZT24 and glioma tissues at ZT4 and ZT8 when CRY2 expression was lowest and highest, respectively." (PMID 29100427, 2017). "We still has no clue how these genes get modulated by neutrophil infiltration in brain which might uncover the specific function of CRY2 and NR1D1 on glioma development." (PMID 39043735, 2024). "In view of the findings described, it can be inferred that the expression of the negative circadian regulator Cry2 is altered in gliomas tissues." (PMID 34361055, 2021). "Moreover, Per2 levels in glioma tissues at ZT8 were lower compared to normal brain tissues at ZT12 (t=-3.218, p<0.01) when cry2 expression was highest in both samples." (PMID 29100427, 2017). "We observed that CRY2 levels in irradiated glioma tissue were significantly higher compared to untreated glioma, whereas irradiation did not change CRY2 levels in normal brain tissues." (PMID 29100427, 2017). "Four CCGs (ARNTL, NPAS2, CRY2, and DBP) with rhythmic expression were not only identified as differentially expressed genes but also had significant independent prognostic ability in the overall survival of glioma patients and were highly correlated with glioma prognosis in COX analysis." (PMID 35832846, 2022). "Besides, the expression of eight CCGs (CRY2, DBP, NR1D1, NR1D2, PER2, PER3, RORA, and TIMELESS) was negatively regulated by methylation and positively regulated by CNV in glioma, which is consisting with previous studies that DNA methylation and CNV can promote abnormal gene expression." (PMID 35832846, 2022). "Such an approach would be especially useful as it was shown for the two clock proteins CRY2 and PER2 that the effects of their expression on radiosensitivity were exclusively observed in glioma, but not in healthy brain tissues." (PMID 38378853, 2024).
Anxiety (15 papers, 2012 to 2025). Intense feelings of nervousness, tension, or panic often arise in response to interpersonal stresses. "We observed that CRY2 combinations (CRY2_GG/ZBTB20_TT and CRY2_AG/ZBTB20_TT) showed significantly stronger associations with anxiety in females than in males." (PMID 38102312, 2023). "All other variants (PER2, PER3 VNTR, PER3A, CLOCK3111, CRY1, and CRY2 SNPs) were directly associated with anxiety symptoms following bootstrap analysis." (PMID 35365695, 2022). "Currently, it is however not known, whether the knock-out or the knock-down of CRY2 in the whole organism or specific to a tissue produces any change in anxiety-like or depressive-like behaviors, or how mutated CRY2 proteins influence mood-related behaviors." (PMID 23951166, 2013). "Sex-specific associations of CRY2/ZBTB20 and PER3-A/ZBTB20 with anxiety in females suggest that these combinations are involved in sex-specific pathways." (PMID 38102312, 2023). "Specifically, CRY1 and CRY2 knockout mice have been demonstrated to display increased anxiety-related behavior." (PMID 38094940, 2023). "Cry2 is crucial for normal emotional behavior and is directly associated with anxiety-like behavior and mice with higher anxiety behavior exhibit lower expression levels of Cry2 in the hippocampus in comparison with normal mice." (PMID 35998127, 2022). "On one hand, we have started the assessment of Cry2 knock-out mice and anxiety-ranked inbred-strain mice." (PMID 23133436, 2012). "Similarly, mice with deletions in Cry1, Cry2 or both, displayed changes in anxiety; however, despair-related behaviour was unaffected." (PMID 40092590, 2025). "The results of the current study suggest that decreases in the transcriptional repression of CRY2 by ZBTB20 may lead to greater transcription of CRY2, which exerts direct effects on anxiety through mood-related pathways." (PMID 38102312, 2023). "Motor impairment in the rotarod task has been demonstrated in global Cry1/Cry2 knockout mice, and the authors argued that it may be a consequence of elevated anxiety-like behavior observed in those animals." (PMID 35755440, 2022). "Moreover in an animal study, CRY2 mRNA expression was abnormal when inbred-strain mice with the intrinsic level of high anxiety were deprived of sleep." (PMID 23951166, 2013). "This is in line with the observation that Afterhours mutant mice showed lower anxiety-related behaviors and suggests largely complementary roles of Cry1 and Cry2 with an opposite influence of the circadian transcriptional activators and repressors on anxiety-related behavior." (PMID 24187535, 2013). "It is strengthened further by those which show that the CRY2 gene expression is abnormal when inbred-strain mice with the intrinsic level of high anxiety are deprived of sleep, and when humans with bipolar type 1 disorder do remain depressed after the antidepressant sleep deprivation." (PMID 23133436, 2012). "Overall, our results suggest that the sex-specific anxiety risk conferred by the genotypic combinations involving PER3B, CLOCK3111, and CRY2 genes may be further evidence of direct effects of clock gene binding complexes on downstream mood-related physiological pathways." (PMID 35365695, 2022). "Two of the rules with the highest lift values show the combination of CLOCK3111-TC, CRY2-AG, and PER2-AG as a significant predictor of anxiety." (PMID 35365695, 2022). "For males, the most frequently occurring variants were PER2-GG, PER3B-GG, CRY2-GG, and CLOCK3111-TC, with age, but not MEQ, significantly predicting the risk of anxiety." (PMID 35365695, 2022). "Cry1 or Cry2 single knockout mice showed elevated anxiety in the elevated plus maze, but less prominent compared to mice lacking both Cry1 and Cry2 that displayed robust anxiety-related behaviors across tests." (PMID 24187535, 2013). "Interestingly, Cry2-KO mice showed reduced despair-like behavior and increased anhedonia, but not anxiety-like behaviors." (PMID 37441675, 2023).
Anxiety (continued). "Interestingly, cognitive function and anxiety-related behaviors but none of the other behavioral parameters were also altered in mice lacking either Cry1 or Cry2." (PMID 24187535, 2013). "Currently, it is not known, whether the knock-out or the knock-down of the CRY2 gene in the whole organism or specific to a tissue produces any change in the activity of brown adipose tissue or in anxiety-like or depressive-like behaviors." (PMID 23133436, 2012).
colorectal cancer (15 papers, 2013 to 2022). A primary or metastatic malignant neoplasm that affects the colon or rectum. "Similarly, as in the case of cry1, oncogenic effects were predominantly referred with respect to the cry2 gene, as worse survival was associated with high cry2 expression in colorectal cancer tissue." (PMID 36361993, 2022). "A previous study based on human colorectal cancer tissues indicated that CRY2 expression was decreased and that high CRY2 expression predicted worse OS, which supported the results of the current study." (PMID 35116071, 2022). "A separate study revealed that FBXW7 binds to CRY2 in colorectal cancer cells, potentially through a direct interaction between the degron motif of CRY2 and the narrow face of the WD40 domain of FBXW7." (PMID 36142478, 2022). "Another study found that mRNA expression levels of Cry2 and Per2 were down regulated in colorectal cancer." (PMID 23626715, 2013). "CRY2 is overexpressed in colorectal cancer samples that are resistant to chemotherapy." (PMID 31014368, 2019). "Moreover, miR-181d expression can also directly target the 3’-UTRs of CRY2 and FBXL3, providing information on its association with colorectal cancer." (PMID 30241461, 2018). "Also, CRY2 was overexpressed in chemoresistant colorectal cancer patient samples suggesting that CRY2 was a potential therapeutic target in cancer treatment." (PMID 29100427, 2017). "However, CRY2 up-regulation is described in chemoresistant colorectal cancer patients." (PMID 35897788, 2022).